PTGS2 (prostaglandin-endoperoxide synthase 2)
Diseases named in the same sentence as PTGS2 in open-access papers (continued):
Sharing a sentence is not in itself a finding about the gene and the disease.
ischemic stroke (continued). "After filtering out the common targets of FIB and Ischemic Strokes, 31 targets were screened for constructing the PPI network, and the top four core targets (CASP3, PTGS2, JUN, and HSP90AA1) were finally determined." (PMID 36467049, 2022). "The expression of three other ferroptosis-related biomarkers, PTGS2, MAP1LC3B, and TLR4, was all upregulated in ischemic stroke patients vs. normal control in the GSE16561 (all p < 0.05) and GSE140275 datasets (all p < 0.05)." (PMID 34707562, 2021). "By constructing a random forest model and performing ROC monofactor analysis, we identified three ferroptosis-related biomarkers, namely, MAP1LC3B, PTGS2, and TLR4, for ischemic stroke." (PMID 34707562, 2021). "ROC monofactor analysis demonstrated a good performance of MAP1LC3B, PTGS2, and TLR4 in the diagnosis of ischemic stroke." (PMID 34707562, 2021). "As a result, the accuracy of MAP1LC3B, PTGS2, and TLR4 in the diagnosis of ischemic stroke was 67.74, 72.86, and 74.25, respectively, in the GSE16561 dataset." (PMID 34707562, 2021). "For example, Prostaglandin Endoperoxide Synthase 2 (PTGS2/COX-2), which is a prostaglandin endoperoxide synthase and a key enzyme in prostaglandin biosynthesis, acts as an important marker of ferroptosis in ischaemic stroke." (PMID 38590315, 2024). "CASP3, PTGS2, JUN, SLC6A4, and HSP90AA1 rank the top five in terms of degree value, indicating that these targets may be the key targets for FIB to treat ischemic strokes." (PMID 36467049, 2022). "Actually, a previous study had reported that MAP1LC3B, PTGS2, and TLR4 may play a vital role in ischemic stroke or served as biomarkers for ischemic stroke and other diseases." (PMID 34707562, 2021). "Moreover, the random forest model suggested three ferroptosis-related biomarkers, namely, PTGS2, MAP1LC3B, and TLR4, for ischemic stroke." (PMID 34707562, 2021). "Interestingly, the expression of PTGS2, MAP1LC3B, and TLR4 was upregulated in ischemic stroke." (PMID 34707562, 2021). "Finally, the non-cooperatively expressed MIF was removed, and PTGS2, MAP1LC3B, and TLR4 were further selected as ferroptosis-related biomarkers for ischemic stroke." (PMID 34707562, 2021).
Cerebral ischemia (22 papers, 2010 to 2025). Restriction of arterial blood supply to the brain associated with insufficient oxygenation to support the metabolic requirements of the tissue. "In mouse models deficient in the PTGS2 gene, cerebral ischemia leads to increased sensitivity to neurotoxicity, enhanced oxidative stress, and exacerbation of neuronal death." (PMID 39233827, 2024). "Therefore, targeting PTGS2 could be a potential therapeutic approach to alleviate neurological damage caused by cerebral ischemia." (PMID 39697434, 2024). "During cerebral ischemia, PTGS2 expression is upregulated, which coincides with the infiltration of inflammatory cells into the damaged brain." (PMID 39847586, 2025). "RELA, AKT1, JUN, PRKACA, PTGS2, RAF1 and CHUK were identified as four key targets associated with ischemic encephalopathy." (PMID 38285889, 2024). "In this study, we used bioinformatics to identify and validate the differential expression of three target genes of miR-202-3p, Ptgs2, Tlr4, and Ccr2, in the cerebral ischemia penumbra of mice." (PMID 37563282, 2023). "Moreover, the inhibition of PTGS2 by highly selective antagonists reduces ischemic damage in both focal and global cerebral ischemia models." (PMID 40864781, 2025). "PTGS2 and IL6, along with their receptors, primarily promote the inflammatory response following cerebral ischemia." (PMID 39847586, 2025). "In order to further explore the specific protective mechanism of PTGS2 knockdown in the progression of IS, we detected the levels of MDA, ROS, GSH and OSI in primary neuronal cells post OGD/R (a model simulating brain ischemia in vitro)." (PMID 38198162, 2024).
viral infection (21 papers, 2011 to 2025). "We also conducted experiments to measure the kinetics of PTGS2 during viral infection at various doses of ATIII." (PMID 21533265, 2011). "Apart from that, we could propose that inhibition of PTGS2 can be a potential therapeutic strategy for viral infection, and the proposed six approved PTGS2 inhibitor drugs can be repurposed for the treatment of SARS-CoV-2 infection." (PMID 32566414, 2020). "Importantly, the PTGS2 inhibiting drugs celecoxib and loxoprofen already reported to be useful for the treatment of viral infection." (PMID 32566414, 2020). "Studies have found significant upregulation of caspase (CASP6), prostaglandin-endoperoxide synthase-2 (PTGS2), and interferon regulatory factor 7 (IRF7) with the pathological process initiated by a bacterial or viral infection." (PMID 39121644, 2024). "This suggests that both an increase in PTGS2 expression and the availability of lipid substrate are required for PGE2 to amplify release of IL-8 during viral infection." (PMID 38179897, 2024). "Studies have found significant upregulation of CASP6, PTGS2, and IRF7 with the pathological process initiated by bacterial or viral infection." (PMID 38393075, 2024).
Insulin resistance (20 papers, 2015 to 2025). Increased resistance towards insulin, that is, diminished effectiveness of insulin in reducing blood glucose levels. "Integration of compound, target, and pathway data positioned IL-6 as a central mediator, interacting with MAPK1, MAPK3, MAPK14, PTGS2, and BCL2, genes associated with inflammation-induced insulin resistance and adipocyte dysfunction." (PMID 41382285, 2025). "PTGS2 significantly contributes to insulin resistance and, when overexpressed, disrupts renal blood flow and hemodynamics, leading to increased renin receptor expression and podocyte injury." (PMID 38890983, 2024). "PTGS2 is a key enzyme that catalyzes the conversion of arachidonic acid to prostaglandins, and it is also an important substance that mediates insulin resistance." (PMID 36386135, 2022). "Among these, PTGS1 and PTGS2 are known to exacerbate chronic inflammation by promoting PGE2 synthesis, which stimulates androgen secretion from theca cells, thus aggravating insulin resistance and metabolic dysregulation." (PMID 41267865, 2025). "Genes with higher degree including VEGFA, PTGS2, JUN, MAPK8, and HSP90AA1 are hub genes of TwHF against DKD, which are involved in inflammation, insulin resistance, and lipid homeostasis." (PMID 33274236, 2020). "The results indicated that the therapeutic efficacy of LTD on DKD might be achieved by decreasing the expression of PTGS2, NF-κB, JNK, and AKT, which might improve insulin resistance, inflammation, and oxidative stress." (PMID 36386135, 2022). "The main components of EGb may act on multiple targets, such as PTGS2, PPARG, DPP4, and GSK3B, to regulate multiple pathways, and play an antiaging role by inhibiting oxidative stress, inhibiting inflammation, and ameliorating insulin resistance." (PMID 32802136, 2020).
adenoma (19 papers, 1999 to 2025). A neoplasm arising from the epithelium. "Stroma-associated PTGS2 showed an almost exclusive luminal distribution, as already observed in adenomas, suggesting a homeostatic role in preserving the mucosal barrier." (PMID 32168749, 2020). "The role of PTGS2 in colorectal carcinogenesis was also studied by assessing the association of three functional polymorphisms in PTGS2 with risk of development of adenoma and CRC." (PMID 25166592, 2014). "NTSR1 and PTGS2 hypermethylation were elevated already in adenomas and the latter one showed an even somewhat higher hypermethylation frequency in adenomas compared to carcinomas, 50% vs. 33%." (PMID 34680073, 2021). "The functional PTGS2 polymorphisms A-1195G (rs689466), G-765C (rs20417), T8473C (rs5275) were assessed in 200 CRC cases, 991 adenoma cases and 399 controls from the Norwegian KAM cohort." (PMID 25166592, 2014). "PTGS2 mRNA levels were higher in mild/moderate adenoma tissue compared to morphologically normal tissue from the same individual (P<0.0001) and (P<0.035) and compared to mucosa from healthy individuals (P<0.0039) and (P<0.0027), respectively." (PMID 25166592, 2014). "In this study we assessed the levels of PTGS2 mRNA in intestinal tissue from healthy subjects and adenoma and carcinoma cases using the Norwegian KAM cohort." (PMID 25166592, 2014). "More specifically, genes with such a therapeutic potential in non-functioning adenomas included CACNA2D4, IDH1, AURKB, GRIA2, PTGS2 and CX3CR1." (PMID 33168897, 2020). "miR-21 was found to be significantly (p < 0.01) upregulated in adenoma and tumour samples compared to the healthy colonic tissue controls and could explain the altered expression of genes for which DNA methylation changes do not appear to play role (e.g. BCL2, MAL, PTGS2)." (PMID 26482433, 2015).
glioblastoma (19 papers, 2015 to 2025). The most malignant astrocytic tumor (WHO grade IV). "The mechanism of tumor invasion and immune resistance involving COL6A3, COL1A1, COL1A2, LRRC15, IDO1, IL-6 and PTGS2 need to be further researched aiming to improve prognosis of aggressive glioblastoma." (PMID 33928021, 2021). "In addition, PTGS2 upregulation is demonstrated to modulate tumor growth by regulating apoptosis and angiogenesis in glioblastoma." (PMID 30038719, 2018). "In glioblastoma (GBM), HIF-2α induced by the prolyl hydroxylase (PHD) inhibitor roxadustat, upregulated ferroptosis regulatory genes such as ACSL4, PTGS2, and CHAC1, to enhance lipid peroxidation and erastin-induced ferroptosis, leading to the suppression of GBM cell growth in vitro and in vivo." (PMID 37048123, 2023). "Interestingly, 3 was able to suppress pro-inflammatory genes, including IL-1α, IL-1β, IL-12, prostaglandin endoperoxide synthase 2 (PTGS-2), and Toll-like receptor 4 (TLR4), as well as the secretion of the pro-inflammatory cytokine IL-6 in LN-18 and T98G glioblastoma cells." (PMID 34067242, 2021).
Hyperglycemia (19 papers, 2012 to 2025). An increased concentration of glucose in the blood. "While Ptgs2 and Ptges mRNA, which encode COX-2 and PTGS2, were induced by hyperglycemia, other enzymes that metabolize arachidonic acid (5-LO, 15-LO, or thromboxane A synthetase 1) were not in the M1-MΦ." (PMID 32814707, 2020). "Stress conditions such as hyperglycemia and ROS induce the expression of PTGS2 increasing PGE2 levels, which further stimulate ROS production." (PMID 35155683, 2022). "Moreover, the top interacting genes are PTGS2, the function of which has been found to be related to hyperglycemia, and COL2A1, the expression of which is related to inflammation." (PMID 33505497, 2021). "Although, aspirin has been shown to normalize hyperglycemia in T2DM, the direct involvement of PTGS2 as a target for DM is still debatable." (PMID 39458839, 2024).
breast tumor (18 papers, 2010 to 2026). "GDF15 was implicated in multiple cancer types and correlates with lymph node metastases in endometrial cancer and overexpression of IGF-2 or PTGS2 mRNAs in breast tumors associated with greater mortality and increased metastatic potential." (PMID 26910917, 2016). "Studies have shown that inhibiting the expression of PTGS2 can inhibit the proliferation, migration, and invasion of breast tumors, which is consistent with our experimental results above." (PMID 40643495, 2025). "It is conceivable that inflammation and/or angiogenesis in the tumor microenvironment contributes to the activation of CXCR4 and PTGS2 in MDMX-overexpressing breast tumor cells." (PMID 30642351, 2019). "Since the P values for IGF2 mRNA was not significant (P > 0.1), the results suggested a positive connection between increased levels of IMP1 and reduced expression of GDF15 and PTGS2 mRNAs in human breast tumors." (PMID 26910917, 2016). "Based on this finding, we further investigated whether PTGS2 is the target gene of LOC610012 in canine breast tumors, and whether LOC610012 exerts its tumor suppressor effect by regulating PTGS2." (PMID 40643495, 2025). "In human breast tumors, IMP1 mRNA could be post-transcriptional regulated and its expression seemed to be correlated with the reduced levels of its associated transcripts, such as PTGS2, GDF15 and IGF-2 mRNAs." (PMID 26910917, 2016). "Correlation of increased IMP1 expression with the reduced levels of its bound mRNAs, such as PTGS2, GDF15 and IGF-2 transcripts, was also observed in human breast tumors." (PMID 26910917, 2016). "To elucidate the biological functions of SQSTM1, GDF9, LINC01125, PTGS2, GVINP1, and TMEM64 in breast tumor cells, we knocked down the expression of the 6-gene signature using shRNA or the negative control in MCF-7 cell lines to assess cell proliferation, migration and invasion in vitro." (PMID 35436939, 2022). "In addition, higher IMP1 protein levels correlated with lower expression of GDF15, PTGS2 and IGF2 mRNAs in human breast tumors." (PMID 26910917, 2016). "Interestingly, the expression levels of PTGS2 (-4.80-fold change) and EGFR (-2.45-fold change) regulated by hsa-mirR128, ABCB1 (-2.21-fold change), IGF1 (-2.19-fold change), and IL6 (-2.85-fold change) regulated by hsa-miR-223, were significantly reduced in breast tumour tissue." (PMID 32577155, 2020). "In the present work, we will analyse the expression of three genes of interest (PTGS2, HBEGF, and ST6GALNAC5) in the FFPE tissue of primary TN phenotype breast tumours with CNS metastasis compared to patients who do not present with cerebral metastasis." (PMID 27170832, 2016).
schizophrenia (18 papers, 2011 to 2024). A major psychotic disorder characterized by abnormalities in the perception or expression of reality. "An apparent close connection between the ketamine and BPC 157 was noted in the genes’ expression analysis in brain tissue, using Nos1, Nos2, Nos3, Plcg1, Prkcg, Ptgs2, and Ptk2 all associated with schizophrenia presentation." (PMID 35884767, 2022). "This was done with the genes’ expression analysis in brain tissue, using Nos1, Nos2, Nos3, Plcg1, Prkcg, Ptgs2, and Ptk2, all associated with schizophrenia presentation." (PMID 35884767, 2022). "A study published in 2004 mentioned that PTGS2 can affect the susceptibility to schizophrenia." (PMID 36421842, 2022). "Finally, the miR-137 validated target PKA signaling gene set (MAPK1, MAPK3, TCF4, and PTGS2) is of particular interest given that enrichment of schizophrenia-risk associated variants within these targets was replicated in an independent cohort." (PMID 25941532, 2015). "We identified a copy number variation segment in a schizophrenia patient involving a concurrent deletion of the PTGS2 and PLA2G4A genes." (PMID 38816399, 2024).
prostatitis (16 papers, 2008 to 2024). An infectious or non-infectious inflammatory process affecting the prostate gland. "We therefore provide evidence that elevated expression of PTGS2 induced by RUNX1 contributes to colorectal tumorigenesis." (PMID 38778047, 2024). "Cyclooxygenase-2 (COX-2, PTGS2) plays an important role in colorectal carcinogenesis." (PMID 18230181, 2008). "Moreover, elevated iron concentration and differential expression of ferroptosis indicators, including GPX4, SLC7A11/Xc−, ACSL4, LPCAT3, and PTGS2, implied that ferroptosis engaged in the development of prostatitis in the context of iron overload and oxidative damage." (PMID 35755168, 2022). "In the rat breast precancerous lesions model, high and low dose RYNXC could also significantly reduce genes and proteins expression of ESR1, PGR, PTGS2, EGFR, and Src." (PMID 30906412, 2019).
infertile (15 papers, 2015 to 2024). "It has been reported that PTGS2 is closely associated with ovulation failure and implantation disorders in infertility." (PMID 36003498, 2022). "PTGS2-deficient females are infertile, with abnormalities in ovulation, fertilization, implantation, and decidualization." (PMID 34573602, 2021). "This is because both of these components can act on the target PTGS2 gene, and the reduction in PTGS2 expression in the cumulus cells of infertile patients caused by EMS may result in a decrease in cyclooxygenase levels, which in turn will result in impaired oocyte capacity." (PMID 36123943, 2022). "This review included a total of 210 infertility women who underwent IVF, with studies using at least three genes of interest - HAS2, GREM1 and PTGS2 - to correlate with oocyte development competency (ODC) outcomes." (PMID 38524634, 2024). "The prostaglandin endoperoxide synthase 2 (PTGS2, COX2) enzyme, involved in the synthesis of PGF2α and PGE2, is highly expressed by Leydig cells from infertile patients as well as during aging." (PMID 36361676, 2022). "Prostaglandin-endoperoxide synthase (PTGS2), also known as COX-2, is related to the pain and infertility of EMs and the PTGS2/ PGE2 axis is considered as the critical target during EMs." (PMID 33859874, 2021). "Decreased PTGS2/COX-2 expression may lead to decreased oocyte quality, which has been suggested as a possible mechanism of EMs-related infertility." (PMID 36817586, 2023). "Female mice lacking either PTGS2 or the PGE receptor EP2 are infertile, showing decreased ovulation, and abnormal cumulus expansion." (PMID 32148554, 2020).
osteosarcoma (15 papers, 2013 to 2025). A usually aggressive malignant bone-forming mesenchymal neoplasm, predominantly affecting adolescents and young adults. "In consistence with the literature, we found EIF4EBP1, MYC, PTGS2 were down-regulated in PAFAH1B3 knockdown osteosarcoma cells, resulting the deficiency in tumor growth and proliferation." (PMID 34136395, 2021). "In addition, zoledronic acid treatment significantly increased PTGS2 protein levels, whereas adding exogenous CoQ10 blocked the zoledronic acid-induced increase in PTGS2 levels in osteosarcoma cells." (PMID 36686696, 2022). "Among them, the key hub genes were ICAM1 (intercellular adhesion molecule 1), HRAS (Ras family small GTP binding protein H‐Ras), PTGS2 (prostaglandin‐endoperoxide synthase 2, also known as COX‐2), and FOS (FBJ osteosarcoma oncogene)." (PMID 36772869, 2023). "Taken together, these data suggest that the proliferative effect of PAFAH1B3 in osteosarcoma is related to the regulation of the expression of EIF4EBP1, MYC, PTGS2 and RPS6KB1." (PMID 34136395, 2021). "Furthermore, the proliferative effect of PAFAH1B3 in osteosarcoma was related to the regulation of the expression of EIF4EBP1, MYC, PTGS2 and RPS6KB1." (PMID 34136395, 2021).